APOE (apolipoprotein E)
Diseases named in the same sentence as APOE in open-access papers (continued):
Sharing a sentence is not in itself a finding about the gene and the disease.
schizophrenia (47 papers, 2009 to 2025). A major psychotic disorder characterized by abnormalities in the perception or expression of reality. "The APOE e4 allele was also associated with a higher risk of schizophrenia diagnosis in older adulthood." (PMID 38473892, 2024). "In contrast, ApoE, a protein that was increased among SZs in our data, has been linked to the etiology of schizophrenia, but its role in metabolic health highlights this protein as a target for further investigation." (PMID 34741130, 2022). "The association between serum ApoA1 and ApoB levels and clinical symptoms in patients with schizophrenia was regulated by the presence of ApoE rs429358 polymorphism." (PMID 34930329, 2021). "The Repeatable Battery for the Assessment of Neuropsychological Status (RBANS) was employed to evaluate the cognition and the SNPStats was used to investigate the association of ApoE rs429358 with schizophrenia." (PMID 34135129, 2021). "Another study also found that there was a highly significant association between ApoE genotype and schizophrenia in a Chinese population." (PMID 34930329, 2021). "There was a significant association between ApoA1 or ApoB levels and cognition in schizophrenia, which was regulated by the ApoE rs429358." (PMID 34135129, 2021). "A previous systematic review and meta-analysis revealed the association between the ApoE ε3 and schizophrenia in Asian population." (PMID 34930329, 2021). "Meanwhile, a highly significant association was found between ApoE genotype and schizophrenia in the Chinese population." (PMID 34135129, 2021). "A study also found that ApoE ε2 genotype was associated with more depressive symptoms in older Chinese schizophrenia patients." (PMID 34930329, 2021). "The APOE E3 genotype is associated with less depressive symptoms and higher serum low-density lipoprotein in Chinese elderly patients with schizophrenia." (PMID 33178131, 2020). "The only variables that showed no significant relation with any baseline brain variable were alcohol consumption, APOE e4 status, and polygenic schizophrenia risk." (PMID 28424895, 2017). "Some of the significant associations with change (namely the APOE e4 allele and the schizophrenia polygenic profile score) were significantly larger than those for level." (PMID 28424895, 2017). "The two genetic factors we studied, the APOE e4 allele and polygenic risk for schizophrenia, showed small-sized relations to neurostructural decline." (PMID 28424895, 2017). "The final predictor list was the following: sex, physical fitness, allostatic load, health conditions, socioeconomic status, prior intelligence, education, smoking, alcohol consumption, APOE e4 status, and polygenic risk for schizophrenia." (PMID 28424895, 2017). "The melting curve-based allele-specific PCR method was applied to a genetic association study of APOE and schizophrenia in a sample of 711 patients with schizophrenia and 665 control subjects from Taiwan." (PMID 27078154, 2016). "This method was applied to a genetic association analysis of APOE and schizophrenia consisting of 711 patients with schizophrenia and 665 control subjects from Taiwan." (PMID 27078154, 2016). "In a recent systematic review and updated meta-analysis of the genetic association of APOE with schizophrenia that consisted of 28 studies, the authors reported a significant protective effect of APOE3 in the Asian population (OR = 0.73, 95% CI = 0.54–0.98)." (PMID 27078154, 2016). "Several case-control studies have been conducted on the genetic association of APOE and schizophrenia." (PMID 27078154, 2016). "For instance, one study of infants 1–3 months old with family histories of schizophrenia found APOE-associated differences in temporal lobe volume, including the hippocampus and entorhinal cortex." (PMID 25339884, 2014).
schizophrenia (continued). "Only few DEGs such as APOE were previously linked to oligodendrocyte (9 out of 93) and/or schizophrenia (18 out of 93), while the majority of DEGs have not yet been investigated for their roles in oligodendrocyte and schizophrenia." (PMID 40819083, 2025). "This supposition is based on the evidence that the same apolipoprotein E genetic polymorphism may be linked to the age at onset in schizophrenia and the likelihood of surviving to advanced age in the general population." (PMID 39376127, 2024). "Moreover, a French association study and meta-analysis showed that only in a male sample, there was an association between schizophrenia and ApoE ε2ε3 genotype." (PMID 34930329, 2021). "In addition, there was an association between undifferentiated type of schizophrenia and ApoE ε3/ε3 genotype in the Serbian population." (PMID 34135129, 2021). "For example, one study found a significant association between ApoE 3 gene variation and schizophrenia in Asian populations; Another study found a significant association between ApoE rs429358 or ApoE rs7412 polymorphisms and low-density lipoprotein levels (LDL) in whites and African Americans." (PMID 34135129, 2021). "We speculated that ApoE polymorphism rs429358 may be involved in the development of schizophrenia and further the relationship between the clinical symptoms and the ApoA1 or ApoB levels in patients with schizophrenia." (PMID 34930329, 2021). "Therefore, the observed relation between ApoE variant status and alterations in ApoA1 levels is specific for patients with schizophrenia." (PMID 34930329, 2021). "Both ApoE ε3 and ApoE-219G haplotypes increased the risk of schizophrenia in siblings." (PMID 34930329, 2021). "In addition, an association between undifferentiated type of schizophrenia and ApoE ε3/ε3 genotype was found in a Serbian population." (PMID 34930329, 2021). "However, few studies explored the effects of ApoE gene polymorphism on blood lipid levels and cognition in schizophrenia." (PMID 34135129, 2021). "Previous studies have shown that ApoE gene polymorphism may affect the level of lipoprotein and also affect the development of schizophrenia." (PMID 34135129, 2021). "However, few studies have explored the effects of ApoE gene polymorphism on blood lipid levels and cognition in schizophrenia." (PMID 34135129, 2021). "Interestingly, both ApoE ε3 and ApoE-219G haplotypes increased the risk of schizophrenia in siblings." (PMID 34135129, 2021). "However, a previous meta-analysis reported an association of ApoE ε3 with schizophrenia in an Asian population." (PMID 34930329, 2021). "The relationship between APOE gene polymorphism and schizophrenia is very complicated." (PMID 33178131, 2020). "Allele frequencies and prevalence of APOE among Chinese elderly with schizophrenia." (PMID 33178131, 2020). "Therefore, a large sample of longitudinal studies is needed to further examine the association between APOE gene polymorphism and schizophrenia." (PMID 33178131, 2020). "Our study showed that the APOE ε2 allele and male sex are possible protective factors against blood lipid abnormalities in the context of atypical antipsychotic use in patients with schizophrenia 60 years or older." (PMID 29233125, 2017). "We evaluated the APOE genotype, blood sugar, blood lipids, and other related indicators to explore the influence of APOE polymorphisms on lipid and glucose metabolism in hospitalized patients 60 years or older with schizophrenia." (PMID 29233125, 2017). "Genetic association studies of APOE variants have been conducted in various psychiatric illnesses, such as major depressive disorder, schizophrenia, bipolar disorder, autism, attention deficit hyperactivity disorder, panic disorder, and post-traumatic stress disorder." (PMID 27078154, 2016).
schizophrenia (continued). "Interestingly, five SNPs located outside of the APOE locus have also been associated with traits related cognitive ability (“cognitive ability, years of educational attainment or schizophrenia (pleiotropy)”, “general cognitive ability”, “intelligence” and “self-reported math ability”)." (PMID 33397400, 2021). "A crucial next step would be to examine APOE transcription in cingulate cortex interneurons in patients with disorders that present with attention and memory symptoms, such as AD, schizophrenia, and ADHD." (PMID 39632090, 2024). "In contrast, ApoE, which is synthesized primarily in the brain, plays an important role in many neurological disorders including schizophrenia, where it is thought to regulate synaptic plasticity." (PMID 34741130, 2022). "Lipid-binding proteins ApoB, ApoD, ApoF, and ApoM were reduced in patients with schizophrenia, whereas ApoE was increased." (PMID 34741130, 2022). "The models of analysis of covariance and multivariate analysis were conducted to investigate the effect of ApoE rs429358 on cognition in schizophrenia." (PMID 34135129, 2021). "The HWE test revealed that the genotype distributions of the ApoE rs429358 in both schizophrenia and controls were consistent with HWE (case: p = 0.52; control: p = 1.0; all: p = 0.82)." (PMID 34930329, 2021). "The HWD test revealed that the genotype distributions of ApoE rs429358 in both schizophrenia and controls were consistent with HWD (case: p = 0.52; control: p = 1.0; all: p = 0.82)." (PMID 34135129, 2021). "APOE hyper-methylation has been identified in several age related pathologies including impaired cognitive function, alzheimeŕs disease and schizophrenia." (PMID 30788380, 2018). "Studies examining the relationship between the APOE genotype and lipid abnormalities in patients with schizophrenia have been inconclusive, but primarily focused on adult patient populations." (PMID 29233125, 2017). "Taken together, these data show that the effects of the APOE genotype on serum blood lipids are consistent between patients with schizophrenia and healthy subjects." (PMID 29233125, 2017). "With lipid-lowering medication used as a covariate, cholesterol was significantly lower in elderly patients with schizophrenia with the APOE ε2 genotype than in those with the APOE ε3 and APOE ε4 genotypes (P < 0.05)." (PMID 29233125, 2017). "Last, the brains of schizophrenia patients with leucotomy formed β-amyloid plaques in gray matter also adjacent to the axotomy site, but predominantly in those patients with the APOE ε4 haplotype." (PMID 27885490, 2017). "Nevertheless, the genetic data of our study shall contribute to future meta-analysis study of APOE and schizophrenia." (PMID 27078154, 2016). "Several genetic association studies report an association between apolipoprotein E (ApoE), which plays an important role in lipoprotein metabolism and CVD, and schizophrenia." (PMID 26137440, 2015). "Changes in apolipoprotein E and D levels in the CNS have previously been reported in patients with schizophrenia and bipolar disorder." (PMID 19715613, 2009). "While genes such as TCF7L2, TNF, APOE and BDNF-related genes can heighten T2DM and schizophrenia risk, other genes may have opposing impacts and lead to inconsistent and biased LDSR findings." (PMID 37477360, 2023). "In conclusion, ApoE rs429358 gene polymorphism did not directly affect the susceptibility to schizophrenia or psychiatric symptoms of schizophrenia." (PMID 34930329, 2021). "In summary, the ApoE rs429358 gene polymorphism did not directly affect the susceptibility to schizophrenia and cognitive function of schizophrenia." (PMID 34135129, 2021). "Furthermore, a longitudinal study found that ApoE-ε4 predicted worsening severity of hallucinations and delusions in patients with schizophrenia in late adulthood." (PMID 34930329, 2021).
schizophrenia (continued). "First, owing to the cross-sectional study design, the causality between ApoE rs429358, ApoA1 and ApoB levels, clinical symptoms in patients with schizophrenia was not directly presented." (PMID 34930329, 2021). "Therefore, future studies are needed to confirm our current findings in larger samples from different ethnics, and the biological mechanisms of clinical symptoms of schizophrenia involved in ApoE rs429358 should be further studied." (PMID 34930329, 2021). "Nevertheless, an early meta-analysis showed an association of ApoE ε3 with schizophrenia in Asian populations, but not in other populations." (PMID 34135129, 2021). "Furthermore, the association between ApoA1 or ApoB levels and psychopathology of schizophrenia was regulated by ApoE rs429358." (PMID 34930329, 2021). "For example, a French association study and meta-analysis suggested that there was no major role for APOE gene variants in schizophrenia as a whole." (PMID 33178131, 2020). "General demographic data of the Chinese elderly with schizophrenia based on APOE E3." (PMID 33178131, 2020). "Therefore, we explored the correlations between the APOE genotype and glucose/lipid metabolism indicators and abnormalities in hospitalized patients 60 years or older with schizophrenia with a history of long-term antipsychotics use." (PMID 29233125, 2017). "In the context of atypical antipsychotics use, carriers of the APOE ε2-genotype and male patients with schizophrenia 60 years or older may be less likely to develop a lipid metabolism abnormality." (PMID 29233125, 2017). "These five schizophrenia patients genotyped either as APOE ε3/3 or ε3/4." (PMID 27885490, 2017). "We did not observe the protective effective of APOE3 against schizophrenia in our present study, nor did we observe the association of other alleles of APOE with schizophrenia." (PMID 27078154, 2016). "Moreover, an association study and meta-analysis revealed an association between schizophrenia and ApoE ε2ε3 genotype in French male samples but not in the entire French sample." (PMID 34135129, 2021). "Therefore, this study aimed to examine whether the ApoE rs429358 affected the development and clinical symptoms of schizophrenia and to explore the relationship between apolipoproteins levels and clinical symptoms." (PMID 34930329, 2021). "Also, the age of patients could be a potential reason, and a meta-analysis indicated that ApoE-ε4 may play an age-mediated pathophysiological role in schizophrenia." (PMID 34930329, 2021). "Therefore, we deduced that even after being administered atypical antipsychotics for a long time, elderly APOE ε2 carriers with schizophrenia may have a lower occurrence of lipid metabolism abnormalities than ε2 non-carriers." (PMID 29233125, 2017). "Furthermore, no other APOE alleles were found to be associated with schizophrenia in this meta-analysis in either Caucasian or Asian samples when analyzed separately or together." (PMID 27078154, 2016). "One previous study indicated that the phenotypes of drug-free schizophrenia patients with and without the ApoE ε4 allele were different, showing that ApoE ε4 + patients had lower positive symptoms as measured by the Brief Psychiatric Rating Scale compared to ApoE ε4- patients." (PMID 34930329, 2021). "The five frequently selected interactions suggest that the sex of a subject was modifying the effects of peptides from APOE, A2AP, HBA, HBG1, and SHBG on the probability of having schizophrenia." (PMID 30745560, 2019). "Model selection using glinternet to allow for first-order interactions identified five peptides from APOE, A2AP, HBA, HBG1 and SHBG whose effect on the probability of having schizophrenia was modified by sex." (PMID 30745560, 2019). "Our study found that ApoE rs429358 genotype groupings had a significant effect on the relationship between serum ApoA1 or ApoB levels and negative symptoms of schizophrenia." (PMID 34930329, 2021).
schizophrenia (continued). "Some researchers have found that the APOE genotype is related to the manifestation of glucose/lipid metabolic abnormalities in patients without schizophrenia." (PMID 29233125, 2017). "All five schizophrenia patients without leucotomies showed minimal or no β-amyloid immunoreactivity in cortical gray matter, including three patients with APOE ε4 haplotype." (PMID 27885490, 2017). "However, the effect of APOE E3 on depressive symptoms has never been investigated in an aging Chinese population with schizophrenia." (PMID 33178131, 2020). "In a meta-analysis of the genetic association of APOE with schizophrenia that consisted of 11 Caucasian and 6 Asian case-control studies, APOE4 was found to have a modest association of risk with schizophrenia in the Caucasian population, but not in Asian population." (PMID 27078154, 2016). "Thus, ApoE genotype may play a role in conferring negative symptoms in schizophrenia by affecting ApoA1 or ApoB levels." (PMID 34930329, 2021). "However, the effect of APOE E3 on depressive symptoms in schizophrenia has never been investigated." (PMID 33178131, 2020). "Plasma TG, remnant cholesterol, and large and medium TRL particle concentrations correlated strongly with apoCII, apoCIII, and apoE in the non-HDL fraction, and with apoCIII and apoE in the HDL fraction in patients with schizophrenia." (PMID 38879166, 2024).